EFEMP1 (EGF-like fibulin extracellular matrix protein 1)
Diseases named in the same sentence as EFEMP1 in open-access papers (continued):
Sharing a sentence is not in itself a finding about the gene and the disease.
chondrosarcoma (1 paper, 2020). A malignant cartilaginous matrix-producing mesenchymal neoplasm arising from the bone and soft tissue. "We also found that the serum EFEMP1 levels in patients with chondrosarcoma were higher compared to those of controls, suggesting that EFEMP1 was potentially involved in the process of chondrogenic differentiation." (PMID 32280689, 2020). "The mean serum level of EFEMP1 in chondrosarcoma patients and patients with giant cell tumor of the bone (SD) was 12.53 (7.56) ng/ml (Supplementary ), which was significantly higher than that of the healthy controls (P < 0.001)." (PMID 32280689, 2020). "To study the specificity of serum EFEMP1 for OS, we compared the serum EFEMP1 level between OS patients and patients with other primary malignant bone tumors, chondrosarcoma, and giant cell tumor of the bone." (PMID 32280689, 2020). "Additionally, patients with either chondrosarcoma or giant cell tumor of the bone had significantly higher serum EFEMP1 levels than OS patients (P = 0.002)." (PMID 32280689, 2020). "Additionally, patients with either chondrosarcoma or giant cell tumor of the bone had significantly higher serum EFEMP1 levels than OS patients." (PMID 32280689, 2020). "Although the serum EFEMP1 levels in OS patients and healthy controls were significantly different, EFEMP1 is not a specific biomarker for OS that can be used to distinguish OS from other skeletal system tumors such as chondrosarcoma and giant cell tumor of the bone." (PMID 32280689, 2020). "However, the correlation between EFEMP1 and chondrosarcoma remains unclear and warrants further investigation in the future." (PMID 32280689, 2020).
cocaine dependence (1 paper, 2015). A psychologically and socially impaired state, with or without physiological changes, that develops as a result of using cocaine and which leads to compulsive behaviors to acquire the substance. "The EFEMP1 gene has not been reported in the genetic analysis of cocaine dependence." (PMID 26658140, 2015).
congenital cataracts (1 paper, 2024). "Interestingly, a transcriptome analysis of neural progenitor cells derived from patients with Lowe syndrome, a multisystem disorder characterized notably by anomalies affecting the eye, including congenital cataracts, identified EFEMP1 as a candidate gene." (PMID 38984127, 2024).
Constipation (1 paper, 2024). Infrequent or difficult evacuation of feces. "In this study, we suggest that EFEMP1/AEFEMP1 deposition is a potential cause of constipation." (PMID 39062824, 2024). "A comprehensive review of patients with confirmed or suspected constipation was conducted to assess contribution of EFEMP1/AEFEMP1 deposition to constipation." (PMID 39062824, 2024). "Because deposition in the muscular layer and around the Auerbach plexus is one of the characteristic deposition patterns of EFEMP1/AEFEMP1, EFEMP1/AEFEMP1 deposition may cause dysmotility and constipation." (PMID 39062824, 2024). "However, studies on the association between constipation and EFEMP1/AEFEMP1 deposition are lacking." (PMID 39062824, 2024).
COVID-19 (1 paper, 2023). A disease caused by infection with severe acute respiratory syndrome coronavirus 2. "Of these, 6 genes were found to be shared between COVID-19 and epilepsy, including SMEK2, PNPT1, EFEMP1, CCDC85A, VRK2, and BCL11A, all located on chromosome 2." (PMID 37781245, 2023). "Further, FUMA analysis identified six overlapping genes, including SMEK2, PNPT1, EFEMP1, CCDC85A, VRK2, and BCL11A, shared between COVID-19 and epilepsy." (PMID 37781245, 2023).
cutis laxa (1 paper, 2021). Cutis laxa (CL) is an inherited or acquired connective tissue disorder characterized by wrinkled, redundant and sagging inelastic skin associated with skeletal and developmental anomalies and, in some cases, with severe systemic involvement. "We report the case of a 9-year-old boy with a discernible connective tissue disorder characterized by cutis laxa (CL) and multiple herniations and caused by biallelic loss-of-function variants in EFEMP1." (PMID 33807164, 2021).
diabetic nephropathy (1 paper, 2023). "In this study, GHR, VEGFA and EFEMP1 were identified as potential biomarkers for diagnosing and treating diabetic nephropathy." (PMID 37404805, 2023).
ear infection (1 paper, 2020). A viral or bacterial infection that affects the external, middle, or inner ear. "Another EFEMP1 GWAS association that may have a strong anatomical basis is susceptibility to childhood ear infections (CEIs), a tendency that could in part relate to the specific shape of the eustachian tube." (PMID 32911658, 2020).
Ewing sarcoma (1 paper, 2024). A small round cell tumor that lacks morphologic, immunohistochemical, and electron microscopic evidence of neuroectodermal differentiation. "Knockdown of ETS1 or inhibition of ETS1 with a pan ETS inhibitor TK216 (currently in phase I clinical trial (NCT026570095) for Ewing sarcoma), downregulated AXL, IL6, and EFEMP1, suggesting ETS1 transcriptionally activates these genes." (PMID 38762181, 2024).
geographic atrophy (1 paper, 2022). "Genes with common risk alleles associated with geographic atrophy and neovascular AMD were upregulated in geographic atrophy RPE cells, including CFH, HTRA1, EFEMP1, and APOE, which provide further evidence of their involvement in the pathogenesis of geographic atrophy." (PMID 35882847, 2022).
Hiatus hernia (1 paper, 2022). The presence of a hernia in which the upper part of the stomach, i.e., mainly the gastric cardia protrudes through the diaphragmatic esophageal hiatus. "Locus 2p16.1 (EFEMP1) imparted susceptibility to inguinal and hiatus hernia phenotypes, was significantly associated in both overlap and umbrella cohort analyses, and was also identified in metaUSAT meta-analysis." (PMID 36584111, 2022).
ischemic cardiomyopathy (1 paper, 2025). Ischemic cardiomyopathy is a cardiomyopathy in which a weakness in the muscle of the heart due to inadequate oxygen delivery to the myocardium with coronary artery disease being the most common cause. "Moreover, to further explore the relationship between EFEMP1 and METTL14, we comprehensively analyzed multiple public datasets, including patients with ischemic cardiomyopathy (GSE263297) and young and aged mouse hearts (GSE225576 and GSE289885)." (PMID 40606020, 2025).
keratoconus (1 paper, 2023). A degenerative, structural disorder of the eye, characterized by a cone-shaped protrusion of the cornea. "No 95% CS are defined here for CRF locus 11 (closest gene to lead variant EFEMP1) and locus 100 (closest gene ALDH3A1), the latter also a keratoconus GWAS locus." (PMID 37621707, 2023).
metastasis (1 paper, 2020). The spread or migration of cancer cells from one part of the body (where they first appeared) to another. "The serum EFEMP1 levels were correlated with the Enneking staging system (r = 0.32, P = 0.021) and lung metastasis (r = 0.50, P < 0.001)." (PMID 32280689, 2020).
nonalcoholic steatohepatitis (1 paper, 2025). "EFEMP1 is also a crucial gene involved in the development of nonalcoholic steatohepatitis (NASH) via extracellular matrix (ECM)-related pathways or immunity-related pathways." (PMID 40027189, 2025).
ovarian disorder (1 paper, 2024). A disease involving the ovary. "Our findings revealed distinct cargo compositions in enhanced exosomes, featuring upregulated proteins such as EFEMP1, HtrA1, PAM, and SDF4, suggesting their potential for treating ovarian disorders." (PMID 38793064, 2024).
ovarian dysfunction (1 paper, 2024). The inability of the ovaries to function. "The overexpression of EFEMP1, HtrA1, PAM, and SDF4 in enhanced exosomes compared to naïve exosomes underscores their potential therapeutic relevance in treating ovarian dysfunction." (PMID 38793064, 2024).
ovarian tumor (1 paper, 2013). "EFEMP1 mRNA and protein expressions in normal ovarian tissue, ovarian tumor, high invasive subclones and low invasive subclones were evaluated by immunohistochemistry and real time RT-PCR." (PMID 24236050, 2013). "Serum EFEMP1 levels in patients with ovarian tumor were measured by ELISA assay." (PMID 24236050, 2013).
prostate (1 paper, 2014). "Herein, we sought to characterize EFEMP1 as biomarker for PCa, unveiling its biological relevance in prostate carcinogenesis." (PMID 25211630, 2014).
type 2 diabetes (1 paper, 2025). "In this work, we identify key pathways (e.g., complement cascade), potential therapeutic targets (e.g., FAM3D in type 2 diabetes), and biomarkers of diabetic comorbidities (e.g., EFEMP1 and IGFBP2) through causal inference, pathway enrichment, and Cox regression of clinical trial outcomes." (PMID 40032831, 2025).
Varicose veins (1 paper, 2024). Enlarged and tortuous veins. "After observing the association of the EFEMP1 with varicose veins, we further ensued to identify all genetic variants within EFEMP1 to uncover the additional variants associated with this trait." (PMID 38609985, 2024). "This study identifies EFEMP1 as a potential gene related to the risk of varicose veins in Indians." (PMID 38609985, 2024). "Variant rs3791679 of EFEMP1 was found to be associated with varicose veins in Indians." (PMID 38609985, 2024).
tumor (99 papers, 2011 to 2026). "EGF-containing fibulin-like extracellular matrix protein 1 (EFEMP1) gene encodes fibulin-3, an extracellular matrix protein with both tumor promoter and tumor suppressor properties." (PMID 40718392, 2025). "EFEMP1 is an extracellular matrix protein, associated with elastic fiber formation and cell adhesion and is considered as a tumor‐suppressor gene." (PMID 38217262, 2024). "Archived paraffin-embedded biopsy specimens of the primary tumour were immunohistochemically stained for EFEMP1 to investigate its association with the occurrence of lung metastasis during the follow-up period." (PMID 38031171, 2023). "In clinical studies, the small size of our patient cohort precluded us from establishing a definite causal relationship between EFEMP1 expression in primary tumour and the development of lung metastases." (PMID 38031171, 2023). "Nevertheless, we observed that patients with EFEMP1-expressing tumours have poorer overall survival, suggesting an association with tumour aggressiveness, which is substantiated by the Kaplan-Meier survival analysis." (PMID 38031171, 2023). "According to our results, high EFEMP1 expressing UTUC is associated with aggressive tumor features and a worse prognosis." (PMID 34204134, 2021). "U251 was chosen to screen EFEMP1 variants for ETSP that retains the parental protein's tumor suppressor function in high proliferating TMC via targeting EGFR and angiogenesis, as demonstrated in our previous studies." (PMID 27713911, 2016). "All the examined EFEMP1 variants (E2, E3, E6, E10, E11, E13, and E15) except E7 showed an enhanced effect in U251 on suppressing s.c. tumor growth." (PMID 27713911, 2016). "More strikingly, our data indicate that the down-regulation of EFEMP1 expression is associated with the suppression of tumor growth and metastasis." (PMID 27270657, 2016). "High EFEMP1 expression status is associated with tumor aggressiveness." (PMID 34204134, 2021). "The role of EFEMP1 has tissue specificity, which may be due to the fact that the functions of tumor-associated genes are determined by the tumor surrounding microenvironment." (PMID 27351229, 2016). "By contrast, to further investigate whether methylation of the EFEMP1 promoter was associated with EFEMP1expression, tumor tissues displaying different methylation status were shown by immunohistochemical staining." (PMID 23840707, 2013). "Furthermore, ETSP from expression of EFEMP1 variant construct E5 would have gained tumor-suppression function in SITC by targeting NOTCH signaling and MMP2-related oncogenic activities and the corresponding function in tumor invasion and cancer stem cell phenotypes." (PMID 27713911, 2016). "In addition to observation of angiostatic effects, additional mechanisms underlying EFEMP1's tumor suppression function that have since come to light include attenuation of EGFR/AKT-mediated growth signaling activities and reduction of MMP-induced cancer cell invasion." (PMID 25594013, 2014). "Western blot results subsequently displayed that HIPK4 knockdown significantly reduced HIPK4, TAp63-pS395, Ki67, MMP2, and MMP9 levels, but elevated EFEMP1 levels in tumor tissues." (PMID 40316017, 2025). "Furthermore, clinical stratification analysis reveals that EFEMP1 expression is significantly higher in G3 (poorly differentiated) tumors than in G2 (moderately differentiated) tumors, reinforcing its association with tumor dedifferentiation and aggressive phenotypes." (PMID 41367615, 2025). "Mechanistically, HIPK4 promoted tumor progression by phosphorylating the tumor suppressor TAp63 at Ser395, leading to decreased expression of EFEMP1, a key extracellular matrix protein with anti-tumor properties." (PMID 40316017, 2025). "CSCC tumor tissues and adjacent tissues were collected from patients with CSCC, and we observed that HIPK4 and TAp63-pSer395 levels were significantly increased in CSCC tumor tissues compared with normal tissues, while EFEMP1 expression was reduced (n = 5)." (PMID 40316017, 2025).
tumor (continued). "In tumor biology, antiangiogenic properties (reduction in angiogenic sprouting) of EFEMP1 have been described." (PMID 38217262, 2024). "Several genes of antiviral immune response pathways such as HLA-B, HLA-C, HLA-DQB1 IFI6, IFITM3, CD74, and tumor suppressor genes EFEMP1 and EGR1, are upregulated in tumor and downregulated in TAS." (PMID 34316327, 2021). "EFEMP1 exerts its tumor suppressor activity by suppression of tumor angiogenesis and inhibition of the EGFR/AKT signaling pathway." (PMID 33827418, 2021). "In order to verify miR-9-induced EFEMP1 downmodulation in this cellular compartment, we performed an IHC analysis on tumor samples from our previous in vivo experiment." (PMID 32972039, 2020). "The epidermal growth factor-containing fibulin-like extracellular matrix protein 1(EFEMP1), functions as an oncogene or a suppressor, depending on the types of tumor." (PMID 32555395, 2020). "Weaponizing EFEMP1 by enhancing its tumor-suppressing role in TMC and reversing its oncogenic role in STIC of GBM is a promising, new, and novel approach to make cancer therapeutics targeting natural cancer evolution strategies." (PMID 32580319, 2020). "In support of these observations, CAFs isolated from human TNBC tumors (GSE37614) presented a lower expression of EFEMP1 in comparison to other tumor subtypes." (PMID 32972039, 2020). "Epidermal growth factor-containing fibulin-like extracellular matrix protein (EFEMP1), also called fibulin-3, has the function in suppressing tumor growth and angiogenesis, while promoting tumor cell invasion." (PMID 33230247, 2020). "We found that the tumor size gradually increased with the progression of the tumor as expected, which coincided with a gradual increase in the serum EFEMP1 levels." (PMID 32280689, 2020). "Down-regulated genes contain markers enriched in mature hepatocytes (Tat, Cyp7a1, Apoa5, Pck1, Cyp3a11, Mup3 or Acsl1) and tumor suppressors (Lect2, Wfdc17 or Efemp1)." (PMID 32372053, 2020). "Functionally, EFEMP1 inhibits migration of tumor cells by regulating MMP2 and MMP9 via ERK1/2 activity." (PMID 32555395, 2020). "Surgical orthotopic implantation was used to generate a mouse OS model, and the correlation between the circulating EFEMP1 levels and tumor progression was examined." (PMID 32280689, 2020). "The serum EFEMP1 level from the 10-day, 20-day, 30-day, and 35-day tumor group of mice was 24.40 (6.40), 23.80 (20.95), 37.40 (23.50), and (14.98) ng/ml (median (quartile spacing))." (PMID 32280689, 2020). "Then, it is likely that EFEMP1 is secreted either from the extracellular exosomes or from dying tumor tissues." (PMID 32280689, 2020). "Since platinum-based therapy is an effective treatment for a subset of TNBCs, we then decided to evaluate the ability of miR-9/si-EFEMP1-induced CAF-like cells to affect tumor cell sensitivity to the anti-cancer drug cisplatin." (PMID 32972039, 2020). "Tumor cells were conditioned for 24 h with the supernatant of NFs miR-9/si-EFEMP1 or controls, and then treated with cisplatin (5 μM, IC50 concentration) for 24h." (PMID 32972039, 2020). "The expression level of EFEMP1 was related to the TNM (the extent of the tumor, the extent of spread to the lymph nodes, the presence of metastasis) stage and the prognosis of patients with HCC." (PMID 30972979, 2019). "The results suggested that HCC cells overexpressing EFEMP1 grew slower than that of the control group, and the size of the tumor was smaller." (PMID 30972979, 2019). "Chi‐squared test and rank sum test were used to analyze the correlation between EFEMP1 protein level and various clinicopathological parameters such as age, sex, tumor size, and TNM stage of HCC patients." (PMID 30972979, 2019). "Dual functions of EFEMP1 was reported in two key tumor cell subpopulations carrying features of STIC and TMC." (PMID 29290950, 2017). "Like EFEMP1, the complementary pleiotrophic tumor suppressive effect of ETSP should be exerted in the tumor’s extracellular compartment." (PMID 29290950, 2017).